ALDH3A1 (aldehyde dehydrogenase 3 family member A1)
Diseases named in the same sentence as ALDH3A1 in open-access papers (continued):
Sharing a sentence is not in itself a finding about the gene and the disease.
tumor (41 papers, 2008 to 2025). "Consistently, Tumor Mutational Burden (TMB) analysis showed KRAS mutations were higher in tumors with high ALDH3A1 and ALDH3B1 expression (76% and 81%, respectively) than in those with low expression (44% and 38%, respectively)." (PMID 40868269, 2025). "Lower expression levels of ALDH3A1 were linked with advancing tumor grade and stages, and the metastatic spread of lymph nodes." (PMID 40657474, 2025). "The chi-square test and Fisher exact test were applied to evaluate the association of ALDH3A1 expression with histological grade, nodal metastasis and pathological tumor stage (pT)." (PMID 40657474, 2025). "Recent years, a large number of studies have found that ALDH3A1 can be considered as a marker for predicting tumor prognosis and associated with poor clinical outcomes of various tumors." (PMID 38191346, 2024). "Moreover, the combination of sh-ALDH3A1 and β-elemene caused a more dramatic inhibition of tumor growth." (PMID 37730658, 2023). "This may play a key role in tumor promotion because elevated expression levels of ALDH3A1 were linked to increased cell growth and survival." (PMID 36685967, 2022). "Taken together, this finding indicates that ALDH3A1 is associated with tumor progression." (PMID 34572930, 2021). "However, ALDH3A1 expression associated with tumor progression and metastasis has extensively been reported." (PMID 34234849, 2021). "Therefore, ALDH3A1 was involved in tumor progression, but ALDH3A1 expression in metastasis LUAD and its associated mechanism remain poorly understood." (PMID 34234849, 2021). "However, several studies confirmed that ALDH3A1 was positively associated with tumor cells' progression, which was found in our research 29-32." (PMID 34234849, 2021). "As validation, tumor epithelium showed upregulation of Krt17 and downregulation of Aldh3a1 relative to healthy tissue, confirming the neoplastic state." (PMID 41279770, 2025). "In the present study, we showed that the expression level of ALDH3A1 was low in OSCC tumors with poor differentiation and nodal metastasis, thereby supporting a role for ALDH3A1 in the propagation of tumor dedifferentiation and metastatic behavior." (PMID 40657474, 2025). "Immunohistochemistry confirmed that the lower expression of GOT1 and ALDH3A1 was consistent with the smaller tumor volume in the Sh1-GOT1 group." (PMID 41327788, 2025). "Overall, our findings suggest that there is a close relationship between ALDH3A1 expression and tumor progression and biological aggressiveness." (PMID 40657474, 2025). "Overall, these data indicate that ALDH3A1 expression declined as the tumor stage advanced, where weak expression became more frequent in later stages." (PMID 40657474, 2025). "Our results showed that the ALDH3A1 expression level tended to decrease as the tumor grade advanced in OSCC (p < 0.001)." (PMID 40657474, 2025). "We founded the subcutaneous graft tumor model to evaluate the role of ALDH3A1 on OSCC growth in vivo." (PMID 38191346, 2024). "Aldehyde dehydrogenase 3A1 (ALDH3A1) is an NAD+-dependent enzyme that is closely related to tumor development." (PMID 37730658, 2023). "Our immunohistochemical staining indicated that ALDH3A1 showed a dramatically higher expression in the tumor tissues than in the normal tissues." (PMID 37730658, 2023). "Three out of the five components of our risk score, ALDH3A1, ALDH3B1 and ALDH16A1, were identified as tumor promoters." (PMID 35116021, 2021). "Decreased ALDH3A1 expression had a major impact on ECAR rate, suggesting that ALDH3A1 was critical for tumor metastasis." (PMID 34234849, 2021).
tumor (continued). "LUAD cell lines transduced with ALDH3A1-sh substantially reduced the tumor cell proliferation, migration, and invasion, suggesting that ALDH3A1 contributes to potential development of LUAD." (PMID 34234849, 2021). "This was consistent with the report that ALDH3A1 carried by exosomes strongly enhanced tumor cell migration and invasion by accelerating glycolysis." (PMID 34234849, 2021). "It was identified using Gene Expression Profiling Interactive Analysis (GEPIA) that ALDH3A1 expression in later-stage tumor tissues was significantly higher than that in early-stage tumor tissues in LUAD patients." (PMID 34234849, 2021). "Our findings collectively uncovered a novel mechanism that orchestrates tumor cells' metastasis, and decreasing ALDH3A1 represented a potential therapeutic target for reprogramming metastasis." (PMID 34234849, 2021). "Our study demonstrated that ALDH3A1 in LUAD tumor samples of patients with M1 was significantly upregulated than in patients with M0." (PMID 34234849, 2021). "In the present study, we found that ALDH3A1 expression was downregulated in OSCC tissues compared to their adjacent non-tumor tissues." (PMID 32201532, 2020). "Further experiments showed that ALDH3A1 acts as a tumor suppressor gene and inhibits EMT via IL-6/STAT3 signaling pathway in OSCC cells." (PMID 32201532, 2020). "We also detected the protein expression of ALDH3A1 by Western blot analysis; the results indicated that ALDH3A1 expression was reduced in the vast majority of detected tumor samples compared with the ANTs from the same patient." (PMID 32201532, 2020). "Taken together, these pieces of evidence indicate a close relationship between ALDH3A1 expression and tumor EMT development and invasion." (PMID 31817719, 2019). "In the spontaneous metastasis model, expression of Id2 and Aldh3a1 was significantly higher in 4T1 brain-derived sublines compared with sublines from lung metastases or primary tumour." (PMID 30642388, 2019). "Here, we found that ALDH3A1 expression in tumor cells induces the overexpression of COX-2 and mPGES1, yielding high PGE-2 levels." (PMID 31817719, 2019). "ALDH3A1 overexpression enhanced PD-L1 output in tumor cells and resulted in reduced proliferation of peripheral blood mononuclear cells when co-cultured with tumor cells." (PMID 31817719, 2019). "Id2 and Aldh3a1 were consistently upregulated in the independent brain-derived sublines compared with both the primary tumour and lung-derived sublines." (PMID 30642388, 2019). "Consistently, in the attempt to link ALDH3A1 expression in tumor cells with systemic immune tone, we analyzed the activation of peripheral mononuclear blood cells (PBMC) against our tumor cellular models." (PMID 31817719, 2019). "In our tumor cell models, ALDH3A1 influences the redox state of cells, as demonstrated by the marked changes of the transcriptome profile, particularly of pro-inflammatory gene expression, including NFkB, COX-2, and mPGES1." (PMID 31817719, 2019). "In this study we show that tumor cells overexpressing ALDH3A1 by the co-option of inflammatory and EMT signaling molecules are fully capable of mounting, in an autonomous manner, an adequate immune response." (PMID 31817719, 2019). "For the 4T1-Luc cells, ectopic expression of Aldh3a1 resulted in a significant increase in tumour cell colonisation of the brain as monitored by ex-vivo IVIS imaging." (PMID 30642388, 2019). "Ablation of ALDH3A1 expression and activity appears to be a new strategy for targeting the tumor immunosuppressive network." (PMID 31817719, 2019). "The ability of ALDH3A1 to function as lipid aldehyde scavenger would provide a survival advantage for disseminating tumour cells encountering adverse conditions." (PMID 30642388, 2019).
tumor (continued). "Of these isoforms, ALDH3A1 was found to be the predominant isoform that was expressed in the primary tumor samples, and this expression was at a much higher level than that of ALDH1A1 or ALDH2." (PMID 28881734, 2017). "We studied the association between tumor pathology and the expression profile of seven phase I and II drug metabolizing genes (CYP1A1, CYP1B1, ALDH3A1, AOX1, GSTP1, GSTT1 and GSTM3) and some of their proteins." (PMID 26580399, 2015). "Over-expression of ALDH3A1 has also previously been found in tumor cells and increased ALDH3A1 expression can lead to cell proliferation." (PMID 24825356, 2014). "In addition, we found a significant inverse relationship between ALDH3A1 expression and tumor stage (pT)." (PMID 40657474, 2025). "Furthermore, immunohistochemical analysis demonstrated high expression of ALDH3A1 in human tumor tissues compared to normal pancreatic tissues." (PMID 40868269, 2025). "2.In addition, we focused solely on tumor tissue, and thus assessing ALDH3A1 levels in blood or serum could further support its potential use as a non-invasive biomarker." (PMID 40657474, 2025). "Thus, in the present study, we aimed to address the need to conduct a comparative analysis of ALDH3A1 expression and the key clinical pathological parameters, i.e., histological grade, tumor stage, and lymph node metastasis." (PMID 40657474, 2025). "Study has shown that ALDH3A1 may be involved in regulating REDOX dependent signal transduction pathways during tumor progression." (PMID 38191346, 2024). "ALDH3A1 is a newly discovered tumor stem cell marker in recent years." (PMID 38099574, 2023). "Furthermore, ALDH3A1 induced energy metabolism reprogramming, promoted tumor growth, and was identified, for the first time, as a target of β-elemene in vivo and in vitro." (PMID 37730658, 2023). "In addition, a DMR-annotated gene (ALDH3A1) related to cell proliferation and tumor promotion was identified." (PMID 36685967, 2022). "ALDH3A1 expression maintained basal ECAR rate in tumor cell." (PMID 34234849, 2021). "This indicates that intrinsic ALDH3A1 activity might drive tumor cells to disable the immunological state of the tumor." (PMID 31817719, 2019). "Thus, ALDH3A1 expression level clearly has a robust impact on these tumor cells functional state, favoring their potential tumorigenicity." (PMID 31817719, 2019). "Finally, to confirm that the expression of Id2 and Aldh3a1 is upregulated in tumour cells colonising the brain in-vivo, 4T1 tumour cells were freshly isolated from the brains, lungs, and primary tumours and immediately analysed by RT-qPCR." (PMID 30642388, 2019). "In sum, the NFkB expression and the PGE-2 and cytokine release pattern suggest a close relationship between the extent of redox metabolism, markedly regulated by ALDH3A1 expression in tumor cells, and the formation of an inflammatory and immunosuppressive milieu." (PMID 31817719, 2019). "Furthermore, while in overexpressing ALDH3A1 tumor cells the EMT markers Zeb1 and cMYC, known to be associated with PD-L1 expression, were upregulated, in ALDH3A1-ablated tumor cells they were downregulated." (PMID 31817719, 2019). "Based on the immune profile acquired by the tumor cells in relation to the ALDH3A1, we evaluated whether PD-L1 levels were also a function of ALDH3A1 expression/activity." (PMID 31817719, 2019). "In agreement with literature data demonstrating that PGE-2 by tumor cells influences the expression and release of immunosuppressive cytokines, we found that ALDH3A1 silencing selectively reduced immunosuppressive cytokines, and increased the production of immune-stimulating ones." (PMID 31817719, 2019). "Consistent with our previous findings, both Id2 and Aldh3a1 were significantly upregulated in tumour cells isolated from the brain compared with the primary tumour, with a higher expression of these genes in the brain-derived cells compared with those isolated from the lungs." (PMID 30642388, 2019).
tumor (continued). "We observed a 70% reduction in the ALDH3A1 activity in the treated tumor lysate." (PMID 28881734, 2017). "Re-introducing either ALDH1A1 or ALDH3A1 into cells restored the tumor growth in xenografts." (PMID 28978015, 2017). "Indeed, the use of AKR1C3 or ALDH3A1 inhibitors has been showing evident therapeutic benefits in preclinical research, highlighting their potential application value in the endeavor towards tumor treatment." (PMID 39164746, 2024). "Moreover, ALDH3A1 also significantly high expressed in tumor tissue compared to normal tissue." (PMID 34234849, 2021). "Accumulating evidence demonstrated that ALDH3A1 could influence tumor cell proliferation 23-26." (PMID 34234849, 2021). "Furthermore, ALDH3A1 down-regulation in human LUAD may affect tumor cell proliferation, migration, and invasion." (PMID 34234849, 2021). "In light of the changes of stem-cell-like/mesenchymal features elicited by varying the intracellular ALDH3A1 levels, we explored whether the enzyme would affect inflammatory pathways known to amplify tumor progression through various mechanisms, including immune escape." (PMID 31817719, 2019). "Moreover, elevated Id2 and Aldh3a1 protein levels were detected by immunoblotting in the original brain-derived sublines as well as in the independent sublines isolated from the brains of tumour-bearing mice." (PMID 30642388, 2019). "Although these data indicate that Id2 and Aldh3a1 expression is required for efficient tumour growth in the brain, they do not address whether these genes play a role in promoting brain colonisation of tumour cells from the circulation." (PMID 30642388, 2019). "To functionally investigate the effects exerted by cell intrinsic ALDH3A1 on the tumor microenvironment, we set up experiments with tagged peripheral blood mononuclear cells (PBMCs) cultured either in conditioned media (CM) derived from tumor cells or co-cultured with irradiated tumor cells." (PMID 31817719, 2019). "Transcriptomic profiling revealed that PDGCOs_1 expressed elevated levels of tumor epithelial and stem cell markers, such as EPCAM, CDH1, ALDH3A1, CA9, CD24, and CD133." (PMID 40723172, 2025). "Some studies have shown that ALDH3A1 promotes glycolysis and lactate accumulation through activation of the LDHA pathway; inhibition of ALDH3A1 reduces lactate levels and inhibits tumor cell proliferation." (PMID 41228459, 2025). "Our results provide valuable insights into the expression of ALDH3A1 in OSCC and its correlations with tumor pathological stage, histological grade, and lymph node metastasis." (PMID 40657474, 2025). "It is further shown that ALDH3A1 and ALDH3B1 are overexpressed in tumor tissues and predict poorer patient outcomes." (PMID 40868269, 2025). "Therefore, ALDH3A1 might be dependent on glycolysis to maintain tumor cell metastasis." (PMID 34234849, 2021). "Western blotting analysis revealed that six proteins (MGST1, MGST3, ABCG2, FXYD2, ALDH3A1, and GST-ω1) were differentially expressed among G1-G4 DDP-resistant tumor tissues." (PMID 32158694, 2020). "Similarly, ALDH3A1 is associated with the overexpression of NFkB and EMT markers such as VIM, FN1, and Zeb1, revealing that the enzyme, through a direct effect on the redox state of tumor cell metabolism, is involved in the process that links stemness, EMT, and inflammation in tumor cells." (PMID 31817719, 2019). "To evaluate the potential function of ALDH1A1 and ALDH3A1 in cell proliferation and tumor growth, we knocked out ALDH1A1 and ALDH3A1, both together (DKO) and individually (1A1_KO or 3A1_KO)." (PMID 28978015, 2017). "Importantly, we confirmed through mechanistic studies that ALDH3A1 is a direct transcriptional target gene of BMAL1, thus establishing a new molecular bridge between core circadian regulation and reprogramming of tumor glucose metabolism." (PMID 41228459, 2025).
tumor (continued). "Moreover, the RT-PCR of tumor tissues showed that mRNA level of ACO2, ATP5B, and MT-ND2 were lower in CRS + Lv-ALDH3A1 than those in CRS + NC group." (PMID 38191346, 2024). "As for the xenograft tumor staining, elevated levels of ALDH3A1 were found in lymph node and bone metastases compared to primary tissues." (PMID 34572930, 2021). "Treatment with oligomycin might enlarge tumor cell ECAR, and we stated that ALDH3A1 still positively affected ECAR rate." (PMID 34234849, 2021). "Vectors of negative control (NC)-sh, ALDH3A1-sh1 and ALDH3A1-sh2 were constructed to analyze the direct regulatory capability of ALDH3A1 for tumor metastasis." (PMID 34234849, 2021). "Additionally, eight genes (ABCG2, ALDH3A1, FXYD2, GST-π1, GST-ω1, HMGCR, MGST1, and MGST3) were upregulated among the G1-G4 DDP-resistant tumor tissues." (PMID 32158694, 2020). "Additionally, the protein expression levels of ALDH3A1 and GST-ω1 varied among the G1-G4 DDP-resistant tumor tissues." (PMID 32158694, 2020). "Our study strongly supports the use of ALDH3A1 as a biomarker to predict lymph node metastasis and prognosis of OSCC patients, and suggests that it could function as a tumor suppressor in OSCC cells." (PMID 32201532, 2020). "Consistent with the gene expression profiling, ectopic expression of either Id2 or Aldh3a1 had no impact on the level of tumour burden in the lung but significantly increased tumour burden in the brain." (PMID 30642388, 2019). "In our samples, the overall gene-expression of ALDH3A1 was relatively low (M = 0.26) compared to the mean expression of the other genes (data not shown) and six out of the 45 tumor samples measured, showed no expression at all." (PMID 26580399, 2015). "However, although lower ALDH3A1 levels were found in tumor tissue, previous studies did not determine the detailed immunohistochemical status of ALDH3A1 expression according to the histological grade, tumor stage, or lymph node metastasis." (PMID 40657474, 2025). "To investigate whether ALDH3A1 expression might be involved in mesenchymal phenotype development, we studied EMT markers (CDH1, Zeb1, VIM, and FN1) at the mRNA expression level in all stem-cell-like tumor cells." (PMID 31817719, 2019). "However, when we measured tumor growth of these cells with deleted ALDH1A1 and/or ALDH3A1, we found that knocking out either gene alone did not inhibit tumor growth." (PMID 28978015, 2017). "Expressions of ABCG2, ALDH1A1, and ALDH3A1 were negatively related with immune infiltration level in HCC, and showed no relation with tumor purity." (PMID 32184801, 2020). "TaqmanTM qRT-PCR studies of UM-C6 tumor cells verified that ALDH1A1 gene expression was reduced 88% versus Luciferase-targeted shRNA transduced control cells, whereas neither ALDH3A1 nor ALDH5A1 gene expression were altered." (PMID 18560594, 2008). "In addition to ALDH1A1, it is noteworthy that ALDH3A1 was demonstrated to be overexpressed in LUAD compared to normal alveolar cells, the most likely cells of origin/stem cells of this tumor." (PMID 31001473, 2019). "Having established that both ALDH1A1 and ALDH3A1 possess the GSH/DHLA-dependent NAD+-reduction activity, we tested whether or not this activity is responsible for the tumor-promoting effects observed for ALDH1A1/3A1." (PMID 28978015, 2017).